HGF (hepatocyte growth factor)
Diseases named in the same sentence as HGF in open-access papers (continued):
Sharing a sentence is not in itself a finding about the gene and the disease.
tumor (continued). "It is established that gene expression undergoes dynamic changes as tumor cells undergo EMT and that this is driven by alterations in the tumor gene regulatory mechanism in response to EMT promoting stimuli e.g., macrophage and platelet derived TGFbeta or HGF." (PMID 29212455, 2017). "Interestingly, tumor microenvironment produces cytokines, chemokines and growth factors, including TNFα, TGFβ, IL-6, FGF, epidermal growth factor (EGF), and HGF." (PMID 29088851, 2017). "In addition, growth factors such as basic FGF, hepatocyte growth factor (HGF), EGF, PDGF, and TGF-β produced from M2-TAMs promote the growth of tumor cells." (PMID 29286292, 2017). "This loop could be established, maintained and regulated in response to numerous environmental signals that are present in the primary tumor niche, such as TGF-β, HGF, and hypoxia." (PMID 26623562, 2016). "However, we found that both mouse HGF and human VEGF were detectable in A549-Luc-BM1 implanted tibia and that the expression of these growth factors tended to increase with tumor progression in the tibia." (PMID 27736957, 2016). "Previously, we found that EH extract impaired hepatocyte growth factor (HGF)-induced cancer cell motility, likely by suppressing the HGF-c-Met signaling pathway, since dysregulation of this pathway promotes tumor formation, growth, progression, metastasis, and therapeutic resistance." (PMID 26976141, 2016). "Several signals from the tumor microenvironment have been shown to trigger EMT processes via specific pathways involving epidermal growth factor (EGF), transforming growth factor (TGF)-β, hepatocyte growth factor (HGF), Notch and Wnt/β-catenin signaling." (PMID 27015552, 2016). "Moreover, KAI1 is able to be bind to c-MET to form a complex or quench the activation of HGF, thus preventing the activation of MACC1 to inhibit the migration of tumor cells." (PMID 27793161, 2016). "Binding of hepatocyte growth factor (HGF) to HGF receptor (c-MET) activates multiple key downstream signaling pathways such as the RAS/MAPK, PI3K/AKT and JAK/STAT, which play critical roles in tumor proliferation and survival." (PMID 27102149, 2016). "Tumor weights in HGF plus curcumin group were significantly lower compared with HGF group (0.39 ± 0.03 g in CUR100+HGF group, 0.13 ± 0.05 g in CUR300+HGF group versus 0.57 ± 0.05 g in HGF group)." (PMID 27525306, 2016). "Constitutive STAT3 phosphorylation in tumor cells is usually driven by the overproduction of key cytokines and growth factors, such as IL-6, IL-10, EGF, HGF, Her2/Neu, and VEGF, or their receptors, as well as aberrantly activated cytoplasmic kinases, such as Src, among others." (PMID 27148255, 2016). "CAFs express growth factors including insulin like growth factor-II (IGF-II), hepatocyte growth factor (HGF), and vascular endothelial growth factor (VEGF), through which they increase tumor proliferation and support stemness in a Wnt- and Notch-dependent matter." (PMID 27308617, 2016). "Stimulated by growth factors EGF and HGF respectively, EGFR/Ras/Raf/MEK/ERK and HGFR/PI3K/AKT pathways converge to phosphorylate BAD that plays a critical anti-apoptotic role in many types of tumor cells." (PMID 27590512, 2016). "The HGF/MET signaling axis may also be involved in tumor progression, as increased MET and HGF expressions and enhanced activation of pro-HGF are all seen in clear cell RCC." (PMID 27338367, 2016). "The receptor is activated by extracellular binding of its ligand hepatocyte growth factor (HGF), leading to downstream signalling of pathways like the phosphoinositide 3-kinase (PI3K)/Akt pathway, stimulating tumour growth, cell survival, proliferation, migration, and invasion." (PMID 27175600, 2016). "To test whether CAPS1 could change the tumor microenvironment, we measured the concentration of stromal cell-derived factor 1 (SDF-1), hepatocyte growth factor (HGF), and transforming growth factor-beta (TGF-β) in the culture supernatant of Huh7 cells." (PMID 27689999, 2016).
tumor (continued). "Relevant findings in our lab demonstrate that HGF/c-Met signaling drives brain CSC phenotype by inducing reprogramming transcription factors and that inhibiting this axis in vivo depletes tumors of their tumor-initiating capacity." (PMID 27158195, 2015). "Although HGF is known to promote proliferation of tumor cells, the lower dose of HGF used in this study did not induce significant tumor cell proliferation." (PMID 26642349, 2015). "Even when using a lower concentration of HGF, which failed to induce tumor cell proliferation, a significant increase in proliferation was confirmed in the presence of CS-E." (PMID 26642349, 2015). "CS-E alone did not induce tumor cell proliferation at the tested concentration, indicating that CS-E augments receptor signaling for HGF." (PMID 26642349, 2015). "The elevation in HGF was independent of dose, drug exposure, dose duration, or tumor type and was only restricted to patients who received onartuzumab rather than those who received placebo." (PMID 28536405, 2015). "There was no observed effect of onartuzumab on circulating HGF levels in xenograft tumor-bearing mice or on endogenous HGF in cynomolgus monkeys; the findings were similar to those in clinical studies." (PMID 28536405, 2015). "Rather than using a ‘one size fits all’ approach however, we propose first that a biomarker such as high HGF concentrations in ascites, or high c-MET/phosphorylated c-MET in tumour samples, be used to select patients for therapy with small molecule c-MET inhibitors." (PMID 26138303, 2015). "Prominent expressions of p-c-Met and HGF were detected within the tumor, but were absent in the non-tumor area of the tissue section (Fisher test, p<0.03, N = 3)." (PMID 25607934, 2015). "As has been demonstrated in murine models, while HGF was secreted by HNSCC tumor-derived fibroblasts, but not by HNSCC cells, MET was expressed and functional in HNSCC cells." (PMID 26319934, 2015). "A cocktail of well characterized tumor growth factors (EGF, HGF, and IGF-1) were analyzed in parallel as a positive control to determine whether freshly-isolated tumor cells were able to respond to growth factor activation ex vivo." (PMID 25807104, 2015). "HGF levels were not significantly correlated with certain parameters, including tumor diameter, invasion depth and ly factors; however, preoperative serum HGF levels were elevated as the disease progressed." (PMID 25592281, 2015). "Inflammatory cytokines, overexpressed by tumor cells recruit monocytes (macrophages), lymphocytes and neutrophils to tumor stroma, where they release VEGF, HGF, metalloproteinase 2 and interleukin 8 which affect endothelial cells and contribute to tumor progression." (PMID 24883045, 2014). "Troglitazone prevented the HGF-induced increase in tumor cell invasion in NT shRNA control cells, but not in the Rab7 knockdown cells." (PMID 24505328, 2014). "A link between ACSVL3 and cancer stem cell phenotype was further established by the findings that ACSVL3 expression was regulated by receptor tyrosine kinase pathways that support GBM stem cell self-renewal and tumor initiation, including EGFR and HGF/c-Met pathways." (PMID 24893952, 2014). "Finally, HGF plays an important role on tumor microenvironment, e.g., acting on MET-expressing endothelial cells and thereby stimulating tumor angiogenesis." (PMID 28548076, 2014). "PI3K is a key downstream signaling molecule in the HGF/MET pathway and significant synergy was observed when ARQ 197 was combined with either GDC-0980 or NVP-BEZ235 in suppressing MPM cell motility and growth and in vivo tumor development." (PMID 25221930, 2014). "Similarly, hepatocyte growth factor (HGF) and c-MET play important roles in the control of tumor growth, invasion and metastasis." (PMID 25162296, 2014).
tumor (continued). "Therefore, HGF/SF typically activates MET in a paracrine fashion, although in some cancers the tumor cells themselves express HGF/SF, which leads to an autocrine loop-type mechanism for MET activation." (PMID 25268161, 2014). "Signal activation by HGF in GEC cell lines and tumor models promotes tumorigenesis and metastases." (PMID 24930887, 2014). "Data shows that induction of HGF expression in RCC via RNA information transferred by MVs is one of important contributors to activation of AKT and ERK1/2 signaling pathways which contribute to the pro-tumor effect of MVs." (PMID 24797571, 2014). "In PTSMT, HGF, THBS1 and VEGFA are all expressed at low levels, indicating that HGF signalling does not contribute significantly to tumour angiogenesis." (PMID 24398114, 2014). "However, it is likely that the requirement for RAS pathway activation for tumor development and progression in humans is achieved in the mouse through the activation of c-MET by HGF over-expression." (PMID 25329316, 2014). "In addition, MACC1 promotes proliferation, invasion and HGF-induced scattering of CRC cells in vitro, as well as tumor growth and metastases formation in mouse xenograft models." (PMID 24005867, 2013). "A variety of factors in the tumor microenvironment could induce EMT, including hepatocyte growth factor (HGF), fibroblast growth factor (FGF), and platelet-derived growth factor (PDGF)." (PMID 24386414, 2013). "Higher HGF levels negatively correlate with survival per biomarker analysis of the SHARP trial and prior data and positively correlate with tumor size; however given that HGF is secreted as an inactive precursor, overexpression alone is unlikely to guarantee pathway dysregulation." (PMID 23606971, 2013). "Overexpression of HGF/SF or c-Met in ovarian cancer cells increases expression of α5 and β1 integrins, urokinase and metalloproteinases (MMP-2 and MMP-9) that have been shown to increase tumor growth and metastasis." (PMID 24373588, 2013). "HGF is a multifunctional cytokine secreted by hepatocytes, it can induce EMT that could weaken tumor cell adhesion and enhance invasion in some tumor models." (PMID 23977005, 2013). "VEGF has been shown to be upregulated by a number of other factors that are released in response to the rapid proliferation of tumor cells; these include transforming growth factor α (TGF-α), fibroblast growth factor 2 (FGF-2), and hepatocyte growth factor (HGF)." (PMID 24062983, 2013). "In the cellular mode, the kinetics measured hint towards short-term HGF/SF induced cell cycle synchronization as opposed to the altered expression in the unsynchronized tumor cells." (PMID 23049908, 2012). "The stimulatory effects of HGF on the motility and invasion of HCC cells are well documented, and activation of cell motility and invasion are also rate-limiting steps of tumor metastasis." (PMID 22912725, 2012). "It remains to be determined whether targeting the HGF/MET axis in MM and other HGF-expressing cancers will interfere with the tumor-induced immune dysfunction through the inhibition of IDO activity." (PMID 23232072, 2012). "Myofibroblasts secreting HGF could also induce a CSC phenotype in differentiated tumor cells, indicating a bidirectional path between CSCs and more differentiated tumor cells." (PMID 22509805, 2012). "In fact, HGF, the ligand for Met, is not expressed in epithelial cells but is secreted by fibroblasts in the tumor stroma." (PMID 22788954, 2012). "It follows that down-regulation of HSULF-1 would enhance tumor growth, and it has been shown that over-expression of HSULF-1 in tumor cell lines inhibits specific, relevant signaling pathways dependent on growth factors including FGF-2, HB-EGF, HGF, and VEGF." (PMID 22873647, 2012). "Coupled with our previous findings, these results suggest that in the PC-3 tumor model, c-Met signaling plays a major role in the metastasis-related behavior irrespective of the HGF status." (PMID 22639908, 2012).
tumor (continued). "Tumor cells are induced to secrete pro-angiogenic factors such as VEGF to form the new blood vessels, and activate an invasive program mediated by the c-Met/HGF (hepatocyte growth factor) pathway." (PMID 22929622, 2012). "When HGF binds to the c-MET receptor it generates MET autophosphorylation leading to activation of the MET pathway enabling cell mobilization and vascularization – two processes that contribute to tumor malignancy." (PMID 22363766, 2012). "Therefore we hypothesized that HGF induces Rac recruitment at ruffling sites, which may prolong the membrane expression of CXCR4/Rac-1, and reduce the CXCR4 endocytosis caused by chemoattractants and/or CXCR4 antibodies, thereby stimulating the chemotaxis and migration of tumor cells." (PMID 22242160, 2012). "Toxicological studies revealed that a daily intravenous injection of recombinant HGF for 4 weeks (i.e., 28 times) did not elicit tumor formation in rats or monkeys (unpublished data)." (PMID 22536224, 2012). "A combined analysis of NSCLC, gastric, and HN tumor measurements did not reveal significant correlations between HGF/c-MET levels and c-MET expression (pearson r = 0.1782; p = 0.2063) or HGF expression (r = -0.021; p = 0.8794)." (PMID 21283737, 2011). "Several candidates could be considered, including for example, IGF-1, HGF and FGF, all of which favor tumor cell survival and proliferation." (PMID 21549007, 2011). "HGF, also known as scatter factor, is produced by non-parenchymal liver cells, and is a multifunctional cytokine of the tumor microenvironment of HCC." (PMID 20667141, 2010). "CAFs secrete tumor promoting effectors such as SDF-1, HGF, and TGF-β into the tumor microenvironment, and they overproduce extracellular matrix, which contributes to tumor rigidity and an altered signaling context thus further promoting tumor progression." (PMID 20352126, 2010). "Secondly, residual hepatic VX2 carcinoma might facilitate rapid tumor progression through induction of overexpression of multiple molecular factors, such as PCNA, MMP-9, VEGF, HGF and IL-6." (PMID 20667141, 2010). "The presence of HGF and EGF in vivo, may have an impact on growth later phase growth (past day 8) or likewise in other tumor models." (PMID 19352430, 2009). "Meanwhile, many studies have confirmed that proteoglycans could combine with lots of cell factors such as HGF, bFGF, VEGF, etc. to participate in the formation of induced angiogenesis, which is the necessary process to trigger tumor invasion and migration." (PMID 20025737, 2009). "In general, paracrine stimulation is the stronger of the two in cancer, because a good number of tumour cell types are known never to express HGF." (PMID 17576468, 2007). "Examination of tumour growth revealed that the frequency of tumours with a high Ki-67 index was significantly greater for stromal HGF-positive tumours than for stromal HGF-negative tumours (P=0.0197)." (PMID 15083185, 2004). "The Ki-67 proliferation index was significantly greater in stromal HGF-positive tumours than in stromal HGF-negative tumours (P=0.0386)." (PMID 15083185, 2004). "The presence of autocrine HGF/SF loop in these tumour cell lines did not influence their spontaneous or HGF/SF-induced mitogenic, motogenic or morphogenic activities." (PMID 9649128, 1998). "Although the ras genotype of tumour cells did not influence the HGF/SF-induced motogenic activity, cell lines with the mutant ras genotype more commonly demonstrated a spontaneous motogenic activity than those with the wild-type ras genotype." (PMID 9649128, 1998). "Upregulation of the HGF/MET signalling pathway significantly promotes OS cell proliferation, not only by directly modulating cell cycle progression but also by enhancing cell survival through activation of the PI3K/Akt pathway, thereby accelerating tumour growth." (PMID 40599602, 2025).
tumor (continued). "It suggests that Ile1102Thr can promote tumor formation in the absence of HGF stimulation and that its tumor‐promoting capacity could be increased under HGF stimulation." (PMID 39980226, 2025). "Hepatocyte growth factor (HGF) not only plays a key role in promoting the proliferation and differentiation of normal cells as a multifunctional factor, but also has attracted much attention because it can significantly enhance the invasion and metastasis of tumor cells." (PMID 40251641, 2025). "Besides these factors, other growth factors such as fibroblast growth factor (FGF), hepatocyte growth factor (HGF), insulin-like growth factor (IGF), and transforming growth factor-beta (TGF-β) also play key roles in hypoxia-induced tumor angiogenesis, driving tumor growth and metastasis." (PMID 40443737, 2025). "Moreover, CAFs promote tumor growth, spread, and invasion by releasing significant levels of mitogenic factors, including fibroblast growth factor-1 (FGF-1) and hepatocyte growth factor (HGF)." (PMID 40369674, 2025). "MET activation by its ligand, hepatocyte growth factor (HGF), triggers a cascade of downstream signalling pathways, including the PI3K/AKT, RAS/MAPK, and STAT3 pathways, which are essential for driving oncogenesis, tumour progression, and metastasis (Reviewed in:)." (PMID 39774381, 2025). "These cells facilitate tumor growth by producing ECM components and secreting a variety of soluble mediators, including transforming growth factor-β (TGF-β), interleukin (IL)-6, and hepatocyte growth factor (HGF), which promote cancer cell proliferation, invasion, and immune modulation." (PMID 41244711, 2025). "Cytokines produced by CAFs, including IL-6, VEGF, IL-8, HGF, and SDF-1, have been identified; therefore, we hypothesized that in CRC, the humoral factors produced by CAFs also promoted the migration of monocytes into the tumor." (PMID 39000110, 2024). "In addition, TAMs also produce a variety of factors that directly stimulate tumor cell proliferation and motility, including FGF, hepatocyte growth factor (HGF), epidermal growth factor receptor (EGFR) family ligands, platelet-derived growth factor (PDGF) and TGF-β." (PMID 39606239, 2024). "Within 500 μm of a blood vessel, tumor cells may perform sustained directional migration towards HGF gradients with or without macrophages." (PMID 39555068, 2024). "Interestingly, tumor cells do not secrete HGF themselves; instead, it is secreted by neighboring cells within the tumor microenvironment in a paracrine manner." (PMID 39469621, 2024). "However, the one-armed 5D5 antibody does not exhibit anti-tumor activity in HGF-independent c-MET activation cases." (PMID 39664377, 2024). "Furthermore, TGFβ plays a key role in tumor-stroma crosstalk and activation of HSCs leads to secretion of cytokines (including TGFβ, stromal derived factor (SDF), platelet derived growth factor (PDGF), HGF and ECM proteins, fibronectin and collagen)." (PMID 38204925, 2024). "Previous studies have reported that irradiated cultured HGF (Hepatocyte growth factor) over-expressing engineered mesenchymal stem cell (HGF-eMSC) exhibited decreased proliferation rates in vitro culture and no tumor was detected in in vivo tumorigenicity testing using nude mice." (PMID 38886817, 2024). "The inflammatory role of neutrophils promotes tumor growth, invasion, angiogenesis, and metastasis by secreting reactive nitrogen species (RNS), proteases, reactive oxygen species (ROS), vascular endothelial growth factor (VEGF), hepatocyte growth factor (HGF), and other cytokines." (PMID 38370351, 2024). "Additionally, various pathways such as MAPK, PI3K/Akt, Wnt/β-catenin, hepatocyte growth factor (HGF)/c-MET, and JAK/STAT contribute to tumor cell phenotypic transitions, forming intricate feedback loops crucial for tumor survival, stemness, EMT, metastasis, and clonal potential." (PMID 39146202, 2024).